NOX4 (NADPH oxidase 4)
Diseases named in the same sentence as NOX4 in open-access papers (continued):
Sharing a sentence is not in itself a finding about the gene and the disease.
pulmonary fibrosis (continued). "Our group previously reported that mice harboring a conditional deletion of NOX4 in macrophages were protected from asbestos-induced pulmonary fibrosis." (PMID 37044213, 2023). "In chronic lung diseases, NF-κB can induce the process of pulmonary fibrosis by mediating the up-regulation of NLRP3 or NOX4." (PMID 37858201, 2023). "Pulmonary fibrosis, therefore, involves oxidative stress, persistence of myofibroblasts and resistance to apoptosis as a result of Nox4/Nrf2 imbalance." (PMID 36552855, 2022). "A function linking macrophage NOX4 to lung fibrosis was also suggested by data demonstrating elevated NOX4 expression in lung macrophages in asbestos patients." (PMID 35740032, 2022). "In the fibrotic lung, elevated levels of reactive oxygen species (ROS)-related factor NADPH oxidase 4 (Nox4) induce lung fibroblasts to transform into a senescent and apoptosis-resistant phenotype, promoting pulmonary fibrosis." (PMID 35563849, 2022). "BRD4 regulates expression of Nox4, an enzyme required for TGFβ-induced production of reactive oxygen species and fibroblast to myofibroblast transition in pulmonary fibrosis." (PMID 35782526, 2022). "In the fibrotic lung, increased Nox4 induces lung fibroblasts to transform into senescent and apoptosis-resistant phenotype, aggravating pulmonary fibrosis." (PMID 35111363, 2022). "JQ1, a nonselective competitive inhibitor of the BET binding pocket, has previously been shown to attenuate TGFβ-induced Nox4 overexpression, oxidative stress and myofibroblast activity in vitro, as well as bleomycin-induced pulmonary fibrosis in mice." (PMID 35782526, 2022). "In pulmonary tissues, ROS are produced by NADPH enzymes and mainly by Nox4, and the excessive production of ROS will contribute to the development of pulmonary fibrosis by participating in the differentiation of MSCs into pulmonary myofibroblasts." (PMID 36552855, 2022). "Reactive oxygen species (ROS) related factor NADPH oxidase 4 (Nox4) has been evidenced to promote pulmonary fibrosis." (PMID 35111363, 2022). "Lung epithelial cells express NOX2 and NOX4, and NOX4 is crucial for epithelial apoptosis and fibroblast to myofibroblast differentiation in bleomycin-induced lung fibrosis in mice." (PMID 33802941, 2021). "MitoQ combined with YFT can improve lung injury in rats with pulmonary fibrosis by reducing the secretion of proinflammatory cytokines and inhibiting TGFβ1/NOX4 and PDGF/ROCK signaling pathways." (PMID 34135982, 2021). "Especially, NOX4 contributes to the pathogenesis of various lung diseases such as asthma, idiopathic pulmonary fibrosis, and Pseudomonas aeruginosa lung infection." (PMID 33567693, 2021). "Sal B was also reported to protect against paraquat-induced pulmonary fibrosis by mediating Nrf2/Nox4 redox balance, as increased Nrf2 expression and reduced Nox4 one, and TGF-β1/Smad3 signalling." (PMID 35126133, 2021). "It has been shown that NADPH oxidase 4 (Nox4) is downregulated in idiopathic pulmonary fibrosis myofibroblasts by Brd4 inhibition." (PMID 34149421, 2021). "Other studies demonstrate that Nox4 is implicated in the profibrotic polarization of macrophages and the genetic removal of Nox4 in macrophages reduces ECM deposition protecting from induced pulmonary fibrosis." (PMID 35126133, 2021). "The in vivo knockdown of Nox4 and pharmacologic targeting of Nox4 during the persistent phase of lung fibrosis in aged mice reduced Bcl-2 levels and restored the capacity of senescent fibroblasts to undergo apoptosis, permitting fibrosis resolution." (PMID 34207528, 2021). "STUB1-mediated degradation of NOX4 inhibits myofibroblast differentiation, which results in bleomycin-induced pulmonary fibrosis." (PMID 34198949, 2021). "In lung fibrosis, Nox4-dependent H2O2 generation is required for TGF-β mediated myofibroblast differentiation and ECM production." (PMID 32041253, 2020).
pulmonary fibrosis (continued). "In lung fibroblasts obtained from idiopathic pulmonary fibrosis (IPF) patients NOX4 contributed to TGF-β1-dependent smooth muscle actin upregulation, resistance to apoptosis and ECM secretion." (PMID 33059312, 2020). "Canonical Wnt signaling and NADPH oxidase 4 (NOX4) have been demonstrated to play a crucial role in the pathogenesis of pulmonary fibrosis including silicosis." (PMID 33376577, 2020). "For instance, SalA downregulates the expression of NADPH oxidase 4 (NOX4), which produces reactive oxygen species in the disease model of pulmonary fibrosis." (PMID 33062143, 2020). "Recent studies have indicated that in pulmonary fibrosis, NOX4/ROS can activate the RhoA/ROCK signalling pathway, promote lung fibroblast migration and collagen synthesis, and enhance pulmonary fibrosis development." (PMID 32496208, 2020). "These clinical findings were corroborated by the fact that NOX4-deficient mice developed significantly less bleomycin-induced pulmonary fibrosis and alveolar epithelial cell death, suggesting the importance of NOX4 in the pathogenesis of pulmonary fibrosis." (PMID 33376577, 2020). "H2O2 generation by NOX4 has been suggested as a key driver in the development of fibrosis and a small molecule drug is under evaluation in clinical trials for idiopathic pulmonary fibrosis and primary biliary cholangitis." (PMID 33059312, 2020). "In mice, the genetic ablation of Nox4 protected against bleomycin-induced pulmonary fibrosis with a concomitant reduction of alveolar epithelial cell apoptosis compared to WT type littermates." (PMID 32360174, 2020). "In lung fibrosis, NOX4/ROS is located upstream of the RhoA/ROCK1 signaling pathway, and the two molecules are oppositely located in renal fibrosis." (PMID 31130857, 2019). "For example, NOX4 is upregulated in idiopathic pulmonary fibrosis, bleomycin-induced lung injury, and lung cancer." (PMID 30669315, 2019). "NOX-4 is an important profibrotic signal implicated in aberrant fibroblast activation in idiopathic pulmonary fibrosis, and TGF-β1-mediated collagen type I gene, α-SMA, and fibronectin-1 gene expressions were Nox4-dependent." (PMID 30915142, 2019). "In the mouse experiment, the inhibition of NOX4 expression by SiNOX4 administration attenuated lung fibrosis and pleural inflammation." (PMID 30669315, 2019). "In idiopathic pulmonary fibrosis, NOX4 also mediates TGF-β-induced fibroblast differentiation into myofibroblasts and contributes to myofibroblast differentiation by activating multiple signal pathways such as Smad 2/3 phosphorylation, JNK, and P38MAP kinase." (PMID 30669315, 2019). "In agreement with this, the use of a low-molecular-weight NOX4 inhibitor in mice attenuates the bleomycin-induced pulmonary fibrosis." (PMID 27345301, 2016). "An excessive expression of NOX4 was reported in both of cardiovascular and pulmonary diseases, including atherosclerosis, pulmonary fibrosis, pulmonary hypertension, and COPD." (PMID 27656649, 2016). "BLM treatment induced development of lung fibrosis with concomitantly enhanced NOX4 expression and SMAD phosphorylation, which was efficiently inhibited by metformin." (PMID 27576730, 2016). "In summary, we elucidated that metformin, an AMPK activator, attenuates lung fibrosis development by inhibiting TGF-β signaling through NOX4 suppression." (PMID 27576730, 2016). "Recent papers also demonstrated potential therapeutic implications for a low-molecular weight NOX4 antagonist in prevention of bleomycin (BLM)-induced lung fibrosis." (PMID 27576730, 2016). "Next, mouse models of BLM-induced lung fibrosis were used to examine the anti-fibrotic action of metformin via NOX4 modulation." (PMID 27576730, 2016). "NOX4 has been recognized to be involved in the proliferation of vascular smooth muscle and fibroblast in pulmonary fibrosis and asthma." (PMID 27656649, 2016).
pulmonary fibrosis (continued). "This study demonstrated that DBTG attenuated BLM-induced pulmonary fibrosis via regulating oxidative stress by inhibiting NOX4." (PMID 26347805, 2015). "In fact, recent evidence indicates that increased NOX4 expression is involved in lung fibrotic remodeling in idiopathic pulmonary fibrosis." (PMID 26192616, 2015). "Both NOX1 and NOX4 are key players in epithelial cell death, leading to pulmonary fibrosis and acute lung injury." (PMID 23671702, 2013). "Recent studies indicate that NOX4 plays a role in the signaling pathways involved in pulmonary fibrosis pathophysiology." (PMID 24027357, 2013). "NOX4 is induced in ischemic stroke, in pressure overload of the heart, and in a bleomycin model of lung epithelial toxicity resulting in lung fibrosis." (PMID 22648375, 2012). "Nox4 expression is robustly increased in pulmonary fibroblasts from patients with idiopathic pulmonary fibrosis and also in rodent models." (PMID 23125837, 2012). "Elevated expression of Nox4 has been reported in a number of cardiovascular diseases, including atherosclerosis, pulmonary fibrosis, and hypertension, cardiac failure and ischemic stroke." (PMID 23125837, 2012). "Inhibition of Nox4 using genetic or pharmacological approaches prevents lung fibrosis and suggests a prominent role for Nox4 in the pathogenesis of pulmonary fibrosis." (PMID 23125837, 2012). "Consequently, STUB1-mediated degradation of NOX4 inhibits myofibroblast differentiation, playing a key role in reducing bleomycin-induced pulmonary fibrosis." (PMID 40901482, 2025). "Ongoing clinical trials of NOX inhibitors include tests with GKT137839, also known as setanaxib, a preferential direct inhibitor of NOX1 and NOX4, in patients with primary biliary cholangitis and idiopathic pulmonary fibrosis (NCT05014672 and NTC03865927, respectively)." (PMID 39456409, 2024). "Moreover, it has been reported that in many CVDs, including atherosclerosis, pulmonary fibrosis and hypertension, heart failure and ischaemic stroke, the expression of NOX-4 is elevated." (PMID 38169375, 2024). "Notably, NOX4-derived ROS are essential for BLM-induced pulmonary fibrosis, and they not only damage airway epithelial cells (AECs) but also participate in downstream fibrotic signaling pathways, such as the TGF-β1/SMAD pathway." (PMID 38166847, 2024). "The underlying mechanism is presumably as follows: Abnormally activated Notch signaling regulates the expression of NADPH oxidase 4 (Nox4), which further affects ROS production; the overproduction of ROS leads to cell death, thus affecting the occurrence of pulmonary fibrosis." (PMID 39139588, 2024). "In this study, the NOX4 inhibitor DPI alleviated BLM‐induced pulmonary fibrosis in mice." (PMID 38286745, 2024). "Notably, pulmonary macrophages from individuals with asbestosis-induced pulmonary fibrosis exhibit elevated expression of NOX4, which contributes to apoptosis resistance in monocyte-derived macrophages and the progression of pulmonary fibrosis." (PMID 38348042, 2024). "Targeting NOX4 promotes the regression of pulmonary fibrosis." (PMID 37875506, 2023). "Among them, Nox4 has been demonstrated to play an important role in driving pulmonary fibrosis." (PMID 36830999, 2023). "Therefore, NOX4 has been considered a potential therapeutic target for the treatment of pulmonary fibrosis." (PMID 36830999, 2023). "Several NOX inhibitors have been analyzed in recent comprehensive reviews but only a few selective antagonists for NOX2 and NOX4 isoforms have been synthesized, and only one (GKT137831, a specific inhibitor of NOX1 and NOX4) is in human clinical trials (phase 2) for pulmonary fibrosis and cirrhosis." (PMID 37838279, 2023).
pulmonary fibrosis (continued). "have shown that nanoplastics in the air are easily inhaled and accumulate in the alveoli of humans and animals and induce the epithelial–mesenchymal transition of human alveolar epithelial A549 cells through NADPH oxidase 4 (NOX4) and ROS, thereby promoting the occurrence of pulmonary fibrosis." (PMID 37457660, 2023). "NOX4 also has a role in other murine models of pulmonary fibrosis." (PMID 37044213, 2023). "Others reported that silencing NOX4 in fibroblasts attenuated bleomycin-induced pulmonary fibrosis." (PMID 37044213, 2023). "ROS derived from NOX1 and NOX4 are key mediators of liver, kidney and lung fibrosis." (PMID 36658776, 2023). "Moreover, the existing research found that metformin exhibited pleiotropic mechanisms for alleviating lung fibrosis, such as NOX4 inhibition, IGF-1 suppression, and mTOR inactivation, and so on." (PMID 36091775, 2022). "From the family members of the NOX, the isoforms Nox1, Nox2 and Nox4 have been found to be implicated in the pathogenesis of pulmonary fibrosis but not Nox3." (PMID 35126133, 2021). "In addition, NOX4-deficient mice show decreased pulmonary fibrosis and AEC cell death in a mouse model of bleomycin-induced lung fibrosis." (PMID 34829703, 2021). "Hecker confirmed the effect of ROS‐induced Nox4–Nrf2 redox imbalance in persistent lung fibrosis." (PMID 33736642, 2021). "Because azithromycin inhibits autophagy, which activates STUB1, it may be a potential therapeutic drug for pulmonary fibrosis by promoting degradation of both NOX4 and Smad3." (PMID 34198949, 2021). "In pulmonary fibrosis, NOX4/ROS is an upstream signalling pathway of RhoA/ROCK1." (PMID 32496208, 2020). "In murine models of pulmonary fibrosis, suppression of Nox4 by siRNA or pharmacologic targeting of endogenous Nox by Diphenylene iodonium (DPI) (a well-validated pan-Nox inhibitor) or GKT137831 (putative dual Nox4/Nox1 small-molecule inhibitor) mitigate the development of fibrosis." (PMID 32360174, 2020). "In addition, the inhibition of NOX4 attenuated pulmonary fibrosis in a bleomycin-induced rat lung fibrosis model." (PMID 33376577, 2020). "Moreover, it has been suggested that intraperitoneal administration of metformin attenuates bleomycin-induced lung fibrosis in mice via NADPH oxidase 4 (NOX4) suppression." (PMID 31278260, 2019). "Since TGF-β signaling plays a pivotal role in airway modeling of chronic pulmonary diseases including COPD, pulmonary fibrosis, and asthma, which also interacted with NOX4 signaling, the expression of TGF-β in ASM of small airway was determined by IHC and immunoblotting assays." (PMID 27656649, 2016). "In keeping with our studies, Nox4 has been shown to play a role in liver and pulmonary fibrosis." (PMID 23991195, 2013). "Thus, a model-independent role of NOX4 in lung fibrosis needs to be tested in different models of the disease." (PMID 22648375, 2012). "In addition, Cos attenuates heat‐killed Staphylococcus aureus‐induced acute lung injury via inhibition of macrophage activation and displays anti‐fibrotic activity in bleomycin‐induced pulmonary fibrosis by regulating NF‐κB and Nrf‐2/NADPH oxidase 4 (NOX4) signalling pathways." (PMID 36810875, 2023). "Furthermore, the deletion of Nox2 or Nox4 in mice is protected from BLM-induced lung fibrosis." (PMID 36552670, 2022). "JHG could also ameliorate pathological changes and collagen deposition in bleomycin-induced pulmonary fibrosis rats, and inhibited NADPH oxidase 4 (NOX4) levels and increased the nuclear factor erythroid 2-related factor 2 (Nrf2) in lung tissues could also be found." (PMID 36056382, 2022). "However, the role of NOX4/ROS in kidney fibrosis is different from that in pulmonary fibrosis." (PMID 32496208, 2020).
pulmonary fibrosis (continued). "An oral treatment with a Nox4 inhibitor substantially reduced the extent of fibrosis and expression of TGFβ-activated fibrotic markers, such as collagen and fibronectin, in a preclinical model of bleomycin-induced lung fibrosis, hence highlighting a role of Nox4 in TGFβ and lung fibrosis." (PMID 33202904, 2020). "The activation of NOX4 was along with the generation of hydrogen peroxide (H2O2), myofibroblast differentiation, contractility, and ECM production in response to TGF-β1 in human myofibroblasts, and therapeutic targeting NOX4 could protect animal models from injury-provoked pulmonary fibrosis." (PMID 27656649, 2016). "One study found that PS-NPs activate NADPH oxidase 4 (NOX4), leading to mitochondrial dysfunction and endoplasmic reticulum (ER) stress, ultimately inducing EMT in A549 cells, a critical step in pulmonary fibrosis." (PMID 41304465, 2025). "In murine models, overexpression of hepatocyte growth factor (HGF) and inhibition of profibrotic NADPH oxidase 4 (NOX4) in VECs creates a modified vascular microenvironment in the liver and lung tissue that promotes liver and lung fibrosis." (PMID 40114970, 2025). "Mice with BLM‐induced pulmonary fibrosis were treated with pirfenidone, metformin, pirfenidone plus metformin and the NADPH oxidase 4 (NOX4) inhibitor diphenyleneiodonium chloride (DPI)." (PMID 38286745, 2024). "Targeting NOX4-derived ROS and disrupting the self-perpetuating loop between NOX4, ROS, and NLRP3 inflammasomes are potential strategies for intervening in the pathogenesis and progression of pulmonary fibrosis." (PMID 38166847, 2024). "The hESC-MSC-IMRC-CM-mediated amelioration of pulmonary fibrosis was through a mechanism by suppressing the BLM-induced oxidative stress and inflammation via respective Nox4/Nrf2 and Toll/MyD88 signaling pathways." (PMID 36830999, 2023). "In a bleomycin-induced mouse model, metformin attenuated NOX4 upregulation and SMAD phosphorylation, resulting in the amelioration of lung fibrosis development." (PMID 37077349, 2023). "Importantly, quercetin is also described as a potent inhibitor of NOX4, which is found upregulated in fibroblast foci as well as the AECII of IPF lungs, and the full deficiency of Nox4 has been shown to protect mice against bleomycin-induced AECII apoptosis and lung fibrosis." (PMID 35626663, 2022). "Nox4 expression is markedly increased in the lung fibroblasts from IPF patients and BLM-induced pulmonary fibrosis mice." (PMID 35111363, 2022). "After treatment with Yifei decoction combined with MitoQ, the signal of TGFβ1/NOX4 and PDGF/ROCK and the development of pulmonary fibrosis were inhibited." (PMID 34135982, 2021). "In this study, we observed the lung injury, collagen content, and TGFβ1/NOX4 and PDGF/ROCK signal pathway of pulmonary fibrosis rats after the administration of Yifei decoction combined with MitoQ." (PMID 34135982, 2021). "In this experiment, we confirmed that the expression of TGFβ1, NOX4, PDGF, and ROCK increased significantly in the rat model of pulmonary fibrosis." (PMID 34135982, 2021). "In the study of lung diseases, NOX4/ROS can activate the RhoA/ROCK1 signal pathway, promote the migration of pulmonary fibroblasts and collagen synthesis, and aggravate pulmonary fibrosis." (PMID 34135982, 2021). "In order to determine the changes of TGFβ1/NOX4 and PDGF/ROCK signal pathway in idiopathic pulmonary fibrosis after Yifei decoction combined with MitoQ intervention, we detected the expression levels of TGFβ1, NOX4, PDGFR-β, and ROCK1." (PMID 34135982, 2021). "Further studies are essential to determine potential interactions between SPHK1/S1P/YAP1 and NOX4 in the modulation of TGF-β mediated mtROS and pulmonary fibrosis." (PMID 32192225, 2020). "Similar to CTGF, it is IL11 and NOX4 that are regulated by PPP lysates that mediate the effects of TGF-β on cardiovascular and liver fibrosis, and acute kidney injury and pulmonary fibrosis, respectively." (PMID 32781631, 2020).